HBA2 (hemoglobin subunit alpha 2)
Diseases named in the same sentence as HBA2 in open-access papers (continued):
Sharing a sentence is not in itself a finding about the gene and the disease.
thalassemia (continued). "More accurate thalassemia screening values for HbA2 and HbF are needed." (PMID 35414613, 2022). "Compared to conventional methods, SMRT technology detected more abnormal hemoglobin variant sites on the HBA1, HBA2, and HBB genes, which illustrated the value of SMRT technology in the diagnosis of common and rare types of α-thalassemia and β-thalassemia variants." (PMID 34690349, 2022). "Trio-WES found no mutations for thalassemia-related genes such as HBA1 and HBA2 for α-thalassemia and HBB for β-thalassemia." (PMID 36385762, 2022). "In Indonesian Guideline for Management of Thalassemia (2018), possibility of thalassemia traits is identified by HbA2 examination: an HbA2 level between 3.6 and 4.2% suggests mild β+-thalassemia and levels between 4 and 9% suggest heterozygote β0-thalassemia and severe β+-thalassemia." (PMID 35573052, 2022). "Co-transfection of HSC with this β-globin transgene and ribonucleoprotein containing sgRNA designed to delete the HBA2 gene resulted in an improvement of α/β globin chain to near-normal levels in erythroid cells of patients with β+-thalassaemia and β0-thalassaemia." (PMID 34713267, 2021). "In southern China, the most prevalent variants of α-thalassemia are -α3.7 deletion, --SEA deletion, -α4.2 deletion, HBA2 c.369C>G, and HBA2 c.427T>C, while those of β-thalassemia are HBB c.126_129delCTTT, HBB c.52A>T, HBB c.316-197C>T, HBB c.-78A>G, and HBB c.79G>A." (PMID 33546747, 2021). "Hb Paksé is a rare form of non-deletional α-thalassaemia characterised by mutations at the termination codon of the HBA2-globin gene (TAA → TAT), resulting in an extended polypeptide." (PMID 32600445, 2020). "Cellulose acetate hemoglobin electrophoresis and HPLC analysis of cell lysates showed that mock and GFP vector-transduced β-thalassemia cells produced HbF and some HbA and HbA2 (α2δ2), which is consistent with these patients having a β+/β0 or β+/β+ thalassemia genotype." (PMID 32154328, 2020). "The increase in HbA2 becomes an important parameter for thalassemia carrier identification." (PMID 31399060, 2019). "Nevertheless, the HbA2 analysis is the gold standard in the diagnosis of thalassemia." (PMID 24093062, 2013). "Possibility of an α-thalassemia trait could be suggested in 11 (1.4 %) cases on the basis of red cell indices and the levels of HbA2 [2.2 (± 0.3)%] which were significantly (P<0.001) lower than normal population 2.9 ± 0.4." (PMID 21150000, 2010). "In our study, conditions such as vitamin B12 deficiency, folic acid deficiency, hyperthyroidism, antiretroviral treatment, calcium deficiency, vitamin C deficiency, and lead nephropathy, which may be related to high HbA2 levels that support Β-thalassemia, were also recorded." (PMID 39926651, 2025). "Among them, HBA2 c.272_279delAGCTTCGG was first reported in Guangxi Zhuang Autonomous Region, China, and the phenotype of HBA2 c.272_279delAGCTTCGG heterozygote was speculated to be similar to -α3.7/αα, showing static thalassemia." (PMID 38660679, 2024). "All 52 cases (of the 72 cases of microcytosis, 52 cases were positive or equivocal for HbA2, which suggested possible BTT) were further subjected to gene study (the ARMS of the most common 22 alleles in the Mediterranean region for detection of beta-globin chain mutation of thalassemia)." (PMID 39463537, 2024). "Receiver operating characteristic analyses were carried out using HbA2 levels to determine the optimal cut-off points to generate the best clinical screening efficiency for males, females, and pregnant women in the group that were either known or suspected thalassemia carriers." (PMID 35414613, 2022). "Finally, we used the estimated allele numbers from within the HbAA subgroup to calculate the sensitivity, specificity, and positive‐ (PPV) and negative predictive values (NPV) for the diagnosis of heterozygous β‐thalassemia on the basis of our various HbA2 cutoffs." (PMID 32394645, 2020).
thalassemia (continued). "The α-globin genes (HBA1, HBA2, and the unique HBA12) were frequently involved in α-thalassemia, with the -α3.7 deletion predominating." (PMID 41929524, 2026). "Thalassemia is classified into two based on the globin gene defect: alpha-thalassemia (Hemoglobin Subunit Alpha 1: HBA1 and Hemoglobin Subunit Alpha 2: HBA2 genes) and beta-thalassemia (Hemoglobin Subunit Beta: HBB gene)." (PMID 40523316, 2025). "The thalassemia genes HBA1 and HBA2 detected in this study are highly homologous, and NGS has certain limitations." (PMID 38660679, 2024). "By way of contrast, in the case of α-thalassemia, Hb electrophoresis test results are normal, and MLPA of HBA1/HBA2 can diagnose the most common deletions." (PMID 36832257, 2023). "In the current study, the mean of Hb, MCV, MCH, and MCHC in β0-thalassemia was lower than β+, besides the RDW, HbA2, and HbF levels were higher." (PMID 35573052, 2022). "Notably, we found that participants with the variant β+ Cap+40–43 (-AAAC) identified by traditional thalassemia genetic testing, did not demonstrate the hematological characteristics of increased HbA2 values or microcytic hypochromic when iron-deficiency is excluded." (PMID 36246595, 2022). "Using family 13 as an example to analyze α-thalassemia, 138 SNPs within 1 Mb upstream and 132 SNPs within 2 Mb downstream from the HBA1 and HBA2 gene were adopted with sequencing depth > 30X." (PMID 35490243, 2022). "Among the deletional genotypes of α‐thalassemia, patients with ‐‐SEA/αα were found to have higher RBC, HbF, and SF and lower Hb, MCV, MCH, and HbA2 than patients with ‐α3.7/αα (p < 0.05)." (PMID 36099017, 2022). "There were statistically significant differences in the mean/median Hb, MCV, MCH, MCHC, RDW, HbA2, and HbF, where Hb, MCV, MCH, and MCHC levels were lower in β0-thalassemia compared to β+-thalassemia." (PMID 35573052, 2022). "Thalassemia is a prevalent inherited disease, which includes α‐ and β‐thalassemia (HBA1, OMIM#141800; HBA2, OMIM#141850; HBB, OMIM#603902), characterized by abnormal globin synthesis." (PMID 34708592, 2021). "Hematological analysis and hemoglobin electrophoresis revealed a mild anemia α0‐thalassemia trait (Hb 90 g/L, MCV 71 fL, and MCH 22.7 pg) compound with β+‐thalassemia trait (MCV 71 fL, MCH 22.7 pg, and HbA2 5.51%) for the pregnant woman." (PMID 32885601, 2020). "Most commonly, α-thalassemia is the result of the deletion of one or both of the α-globin genes, HBA1 and HBA2, located in the telomeric region on chromosome 16 (16p13.3)." (PMID 24456650, 2014). "In α-thalassemia, the deletion locus of the LUC7-like (LUC7L) gene is co-located with Hemoglobin α 2 (HBA2), an α globin gene, resulting in methylation of the HBA2 promoter." (PMID 22735547, 2012). "Traditionally, the diagnosis of HbS/β0-thalassemia requires HbA2 >3.5%, which was not the case in this patient." (PMID 40084327, 2025). "A provisional diagnosis of α-thalassemia was given to 36 participants (0.30%) based on findings of hypochromic microcytic red cell indices, a high RBC count, normal iron studies, and normal/low HbA2." (PMID 40084341, 2025). "Patients with SEA-HPFH combined with α-thalassemia had no or mild anemia, with high HbA2 (2.8–5.3%) and HbF (11–26%) levels." (PMID 38457547, 2024). "And for the αβ-thalassemia, RBC (Cut off≥4.77, PR=44.51%, DR=100.00%), RDW-CV (Cut off≥13.21, PR=22.55%, DR=83.33%), HbA2 (Cut off≥2.90, PR=17.78%, DR=95.83%), formula 5 (Cut off≥ 335.92, PR=46.38%, DR=83.33%), and formula 6 (Cut off≥ 609.79, PR=43.38%, DR= 83.33%) were suitable." (PMID 38699698, 2024). "According to AUC (0.5-0.7, low efficiency; 0.7-0.9, moderate efficiency; > 0.9, high efficiency), RBC was better for screening α-thalassemia carriers while RBC (AUC 0.868), RDW-CV (AUC 0.896), HbA2 (AUC 0.966), and HbF (AUC 0.828) had better efficiency for screening β-thalassemia minor carriers." (PMID 38699698, 2024).
thalassemia (continued). "If someone is heterozygous for --SEA/, their partner, who actually is heterozygous for large deletions including HBA1 and HBA2 in α-globin cluster, is found to be negative via conventional thalassemia gene testing." (PMID 37098594, 2023). "The sensitivity for using the HbA2 cut-off points as a screening marker for α-thalassemia was 55.1% in males, 67.9% in non-pregnant women, 71.3% in pregnant women, and 67.9% in all groups." (PMID 35414613, 2022). "The α–thalassaemia trait (α+–thalassaemia or −α/−α), is known to protect against severe malaria and like HBB-βS, is thus highly prevalent in malaria endemic areas, particularly the 3·7 kb alpha-globin gene (HBA1/HBA2) deletion in Africa." (PMID 33461216, 2021). "Absence of β-globin gene mutation confirmed that there was no carrier in this group and thus none of the β-thalassemia traits was overlooked because of low level of HbA2." (PMID 31941534, 2020). "The proband presented thalassaemia-like hematological features, reduced mean corpuscular volume (MCV 65.6 fl), mean corpuscular haemoglobin (MCH 21.5 pg), increased HbA2 (3.8%), reticulocytes 2.6 (×1000), but haemoglobin concentration (14,8 g/dl) was higher as compared to beta thalassemia carriers." (PMID 22084702, 2011). "The unique complex Corfu δ0β+ allele was first described in one of our patients from the Greek island of Corfu, who presented with non-transfusion dependent thalassemia at the age of 4 years with hemoglobin (Hb) of 9.2g/dL, comprising mainly HbF and low levels of HbA (5.8% with zero HbA2)." (PMID 35336809, 2022). "Indeed, α-thalassemia has been shown to diminish the severity of disease by reducing the amount of sickled RBC, increasing the HbF level and HbA2, and decreasing the intracellular HbS level, which results in a reduction in HbS prompted cellular destruction, thereby improving hemolysis." (PMID 24978191, 2014). "Similarly, five participants with HbA2 > 3.5%, which is a widely used indicator of beta thalassemia trait, turned out to be normal by HRM curve analysis and Sanger sequencing, thereby further demonstrating shortfalls of Hb electrophoresis in detection of thalassemia carriers." (PMID 31941534, 2020). "The phenotype of homozygotes δβ-thalassaemia with co-existing α(+)-thalassaemia dictated FBC results very similar to that of β (+) thalassaemia carrier, and Hb analysis showed >93.0% HbF with total absence of HbA and HbA2." (PMID 39640193, 2024). "Hb Malay carriers do not present any clinical symptoms, only present increased HbA2 and decreased MCV, and are often diagnosed during thalassemia screening." (PMID 36861132, 2023). "However, there are several cases in which patients show typical hematological changes indicating thalassemia (increased erythrocyte count, low MCV and MCH), but have normal HbA2 and HbF and negative gap-PCR." (PMID 24456650, 2014).
anemia (38 papers, 2010 to 2025). A reduction in the number of red blood cells, the amount of hemoglobin, and/or the volume of packed red blood cells. "The heterozygous form of β-thalassemia is associated with a mild persistent anemia and distinctly elevated levels of HbA2, which form the basis for screening programs world-over." (PMID 35354866, 2022). "Carriers of β0 and β+ thalassemia alleles have some hematological phenotypes, such as mild anemia, microcell low pigment red blood cell index, elevated HbA2, or slightly elevated Hb F levels." (PMID 32885601, 2020). "One case with Hb J-Meerut with coexisting nutritional deficiency presented with severe anemia with a Hb HPLC pattern showing decreased HbA2 of 1.8% and an unknown window (P3) peak of 17% with an RT of 1.47 min." (PMID 39439672, 2024). "We discover rare deletions in HBA1/HBA2/HBB associated with anemia." (PMID 34764282, 2021). "We discovered rare deletions in HBA1/HBA2/HBB associated with anemia." (PMID 34764282, 2021). "HPLC: high-performance liquid chromatography; Hb: hemoglobin; RBC: red blood cells; MCV: mean cell volume; MCH: mean cell hemoglobin; RDW: red cell distribution width; HbA2: hemoglobin A2; IDA: iron deficiency anemia." (PMID 40084341, 2025). "This case presented with Hb 121 g/L, MCV 73.8 fL, MCH 24.8 pg, HbA2 2.1%, HbF 17.6%, and Hb New York 28.2%, indicative of mild microcytic hypochromic anemia." (PMID 40524850, 2025). "Beta-thalassemia carrier diagnostic criteria included anemia with MCV <80 fL, MCH <27 pg, and HbA2 Fraction >3.5%." (PMID 38919232, 2024). "Patients with SEA-HPFH combined with β-thalassemia presented with mild anemia, with elevated HbA2 (3.0–3.9%) and extremely high HbF (>95%) levels." (PMID 38457547, 2024). "CPSF6 indirectly modulates glucose homeostasis and insulin secretion, while HBA2, a commonly known marker for anemia and β-thalassaemia, interferes with glycemic markers in T2DM patients." (PMID 37686344, 2023). "The heterozygosity of Corfu δ0β+ is detected in 1–2% of the β-thalassemia carrier population and presents a distinct hematological phenotype of microcytic, hypochromic anemia with normal HbA2 and elevated HbF levels." (PMID 35336809, 2022). "The II4 gene rearrangement was consistent with HBB:c.-78A > G and the individual had microcytic hypochromic anemia, an HbA2 content of 5.5% and an HbF content of 0%." (PMID 36159974, 2022). "The mother’s hematological phenotype was normal, whilst the father (I-2), sister (II-1) and younger brother showed mild hypochromic anemia, increased HbA2 content and slightly increased HbF content in the father (I-2) and sister (II-1)." (PMID 36159974, 2022). "Patient II1 presented with severe microcytic hypochromic anemia, borderline HbA2 (3.6%) and significantly elevated HbF (16.5%); she has required regular transfusions for survival." (PMID 34249106, 2021). "Carrier detection in this study was based upon the presence of microcytic hypochromic anemia, normal serum ferritin level together with HbA2 level of < 3.5%." (PMID 34633587, 2021). "Patients of β-thalassemia minor had milder anemia with decreased total Hb (P < 0.001) and HbA (P < 0.001) and a slight increase in HbA2, E, and F compared to normal subjects." (PMID 22778980, 2012). "Haemoglobin electrophoresis showed a slight increase in HbA2 and F. Since these patients inherit one gene of β-thalassemia, they are either asymptomatic or develop mild-to-moderate anaemia." (PMID 22778980, 2012). "Multiple reports in the literature indicated that participants heterozygous for this variant typically do not exhibit anemia or microcytic hypochromia and often present with normal or elevated HbA2 levels." (PMID 41229428, 2025). "This heterozygous variant was identified in an adult female who exhibited no anemia or microcytic hypochromia and presented with an elevated HbA2 level, consistent with findings reported by Lin and Peng." (PMID 41229428, 2025).
anemia (continued). "The IVS-II-55(T > G) heterozygous variant has been documented in multiple studies, typically in the absence of anemia or microcytic hypochromia, and is often associated with slightly reduced HbA2 levels." (PMID 41229428, 2025). "Alpha thalassemia major (ATM) is an inherited blood disorder caused by the absence of all four α-globin genes (HBA2/1), resulting in severe anemia and lifelong transfusion dependence." (PMID 40967220, 2025). "Although mutations in G6PD and HBA2 are associated with anemia and human disease, SEC14L4 and MYO9B are not previously known to affect RBC function." (PMID 34793330, 2022). "β‐Thalassemia is characterized by microcytic hypochromic anemia as well as increased HbA2." (PMID 32419356, 2020). "Moreover, hisone-year-old son presented a mild anemia (10.7 g/dL) with elevated HbF (8.4%), withmicrocytosis and slightly increased HbA2 (3.6%)." (PMID 32142096, 2020). "I‐1, who was the carrier of both HKαα/‐α3.7 and β41‐42/βN, showed a typical β‐thalassemia trait characterized by increased HbA2 (6.4%) and microcytic hypochromic anemia with mild reduction in mean cell volume (MCV), mean cell hemoglobin (MCH), and mean corpuscular hemoglobin concentration (MCHC)." (PMID 32419356, 2020). "Evaluation of peripheral blood showed microcytic anemia (Hb 10.5 g/dL, MCV 65 fL) but with a normal hemoglobin electrophoresis profile (HbA2 2.9%, HbF 1.1%)." (PMID 40896065, 2025). "Most of the patients were diagnosed with clinical anemia (55.4%), while only 7.7% were diagnosed thanks to neonatal screening for SCD (detection of elevated HbA2 and HbF)." (PMID 38519604, 2024). "The subjects had increased HbA2 values (mean values >4.9%), decreased MCV values (<65 fL), reduced MCH values (<20 pg), and anaemia (mean Hb values of 10 g/dL)." (PMID 36902239, 2023). "The proband was a woman from Foggia, Southern Italy, showing microcytic and hypochromic anemia (MCV 73.0 fL, MCH 22.8 pg), with a normal iron balance and normal HbA2 (2.7%) and HbF (0.3%)." (PMID 36768900, 2023). "Most subjects with high HbA2 values (mean values >5%), low MCV, MCH, and anaemia developed a clinical phenotype of intermediate severity over time." (PMID 36902239, 2023). "The Hb, HbA2, MCV, and MCH of ‐‐SEA/αα were lower than ‐α3.7/αα and ‐α4.2/αα in the three common deletional genotypes, suggesting that the severity of anemia depends on the number of inactivated α‐globin genes." (PMID 36099017, 2022). "In this study, we found a patient showed moderate microcytic hypochromic anemia with Hb 86 g/L, MCV 66.4 fL, and MCH 19.1 pg and decreased level of HbA2 (1.9%) that was suspected to be a α‐thalassemia carrier." (PMID 36099017, 2022). "Its routine blood test revealed microcytic hypochromic anemia with MCV 64.9 fl, MCH 19.2 pg, MCHC 296 g/L, and an increase in HbA2(6.4%)." (PMID 32419356, 2020). "He had presence of blood indices with microcytic-hypochromic anemia: Hb76 g/L, MCV76.2fL, MCH27.3 pg, HbA2 3.4% and HbF65.2%." (PMID 20181291, 2010). "All affected individuals have a variable degree of anaemia (Hb), reduced mean corpuscular haemoglobin (MCH/pg), reduced mean corpuscular volume (MCV/fl) and a normal or slightly reduced level of the minor HbA2." (PMID 20507641, 2010). "In this group, two cases of −α4.2-Hb Q-Thailand/αα were detected, without clinical anemia, microcytic hypochromia, or elevated HbA2 levels." (PMID 41229428, 2025). "Clinically, the presence of microcytic hypochromic anemia, elevated HbA2, and increased HbF levels along with negative results from conventional genetic testing should prompt the use of GAP-PCR to differentiate among the Chinese type, SEA, and Taiwan type." (PMID 41229428, 2025). "The father and sons showed microcytic and hypochromic anemia, with reduced mean corpuscular volume (MCV) 66.2–68.0–70.8 fL, and mean corpuscular hemoglobin (MCH) 21.0–22.7–21.1 pg, but a normal level of HbA2 (2.5–2.8%), while the mother had normal hematologic parameters." (PMID 36768900, 2023).
anemia (continued). "Furthermore, the electrophoretic parameter HbA2-dependent screening may also give rise to false negative or false positive results based on the coinheritance of the α-globin and Krüppel-like Factor 1 (KLF1) genes mutations, the gamma-globin gene promoter mutations, and iron deficiency anemia." (PMID 29295702, 2018).